TMEM239 (transmembrane protein 239)
Tractability: Antibody: UniProt predicts a signal peptide or a membrane-spanning region.
Gene: Protein-coding gene on chromosome 20 (2,816,302 to 2,820,284, forward strand). Ensembl gene ENSG00000198326.
Subcellular location: Membrane
Gene Ontology:
Molecular function: protein binding
Cellular component: membrane
Genetic constraint (gnomAD): Loss-of-function variants: 10 observed, 11.69 expected, observed/expected ratio (o/e) 0.86, 90% interval 0.53 to 1.45. The upper end of that interval is the gene's LOEUF score, 1.45, which puts it in group 5 of 6, group 1 being the genes least tolerant of losing a copy. Missense variants: 183 observed, 176.92 expected, observed/expected ratio (o/e) 1.03, 90% interval 0.92 to 1.17. Synonymous variants: 94 observed, 80.32 expected, observed/expected ratio (o/e) 1.17, 90% interval 0.99 to 1.39.
Homologues: Orthologues: chimpanzee TMEM239 (98% identical), dog TMEM239 (86% identical), rat Tmem239 (86% identical), pig TMEM239 (85% identical), mouse Tmem239 (84% identical).
Diseases named in the same sentence as TMEM239 in open-access papers:
TMEM239 is named in the same sentence as 2 diseases in open-access papers, as found by Europe PMC text mining. Sharing a sentence is not in itself a finding about the gene and the disease. The quoted sentences say what the papers report.
viral infection (1 paper, 2024). "Further studies showed that TMEM239 interacted with the early endosomal marker Rab5A, and that TMEM239 deletion affected the co-localization of viral capsid p72 and Rab5A shortly after viral infection." (PMID 39024394, 2024). "Subsequent virus infection experiments confirmed that virus replication in TMEM239-/- PBMCs was significantly reduced compared with that in WT-PBMCs, whether inoculated with the ad-7GD strain or the WT-HLJ18 strain." (PMID 39024394, 2024).
infection (1 paper, 2024). The state of being infected such as from the introduction of a foreign agent such as serum, vaccine, antigenic substance or organism. "Viral replication in WSL cells increased significantly with prolonged infection, whereas viral replication in TMEM239-/- cells remained at a consistently lower level." (PMID 39024394, 2024).